VPS13C (vacuolar protein sorting 13 homolog C)
Description:
Mediates the transfer of lipids between membranes at organelle contact sites (By similarity). Necessary for proper mitochondrial function and maintenance of mitochondrial transmembrane potential. Involved in the regulation of PINK1/PRKN-mediated mitophagy in response to mitochondrial depolarization.
Synonyms: KIAA1421; FLJ20136; FLJ10381; BLTP5C; PARK23
Tractability: PROTAC: ubiquitination databases record sites on it; its protein half-life has been measured.
Gene: Protein-coding gene on chromosome 15 (61,852,389 to 62,060,473, reverse strand). Ensembl gene ENSG00000129003.
Subcellular location: Mitochondrion outer membrane; Lipid droplet; Endoplasmic reticulum membrane; Lysosome membrane; Late endosome membrane
Gene Ontology:
Molecular function: phospholipid transfer activity
Biological process: mitochondrion organization; negative regulation of type 2 mitophagy; Golgi to endosome transport; intermembrane lipid transfer; macroautophagy; phospholipid transport
Cellular component: cytosol; endoplasmic reticulum membrane; extracellular exosome; late endosome; late endosome membrane; lipid droplet; lysosomal membrane; lysosome; mitochondrial outer membrane; cytoplasm; endosome membrane; dense core granule membrane
Genetic constraint (gnomAD): Loss-of-function variants: 259 observed, 335.04 expected, observed/expected ratio (o/e) 0.77, 90% interval 0.7 to 0.86. The upper end of that interval is the gene's LOEUF score, 0.86, which puts it in group 3 of 6, group 1 being the genes least tolerant of losing a copy. Missense variants: 3,987 observed, 3,766.1 expected, observed/expected ratio (o/e) 1.06, 90% interval 1.03 to 1.09. Synonymous variants: 1,323 observed, 1,303.5 expected, observed/expected ratio (o/e) 1.01, 90% interval 0.97 to 1.06.
Homologues: Orthologues: chimpanzee VPS13C (99% identical), macaque VPS13C (97% identical), dog VPS13C (90% identical), rabbit VPS13C (88% identical), pig VPS13C (87% identical), mouse Vps13c (86% identical), rat Vps13c (85% identical), guinea pig VPS13C (64% identical), tropical clawed frog vps13c (63% identical), zebrafish vps13c (59% identical), Drosophila melanogaster Vps13 (27% identical), Caenorhabditis elegans vps-13 (25% identical). Paralogues in human: VPS13A (36% identical), VPS13D (20% identical).
Diseases named in the same sentence as VPS13C in open-access papers:
VPS13C is named in the same sentence as 34 diseases in open-access papers, as found by Europe PMC text mining. Sharing a sentence is not in itself a finding about the gene and the disease. The quoted sentences say what the papers report.
Parkinson disease (25 papers, 2017 to 2026). A progressive degenerative disorder of the central nervous system characterized by loss of dopamine producing neurons in the substantia nigra and the presence of Lewy bodies in the substantia nigra and locus coeruleus. "The 2 novel pathogenic variants (c.1699C > T, chr15: 62156504–62352664) identified in this study expand the known mutational spectrum of VPS13C-associated Parkinsonism." (PMID 41517720, 2026). "Variants of the VPS13C gene result in a genetic form of Parkinson’s disease, while those of VPS13D lead to an ataxic syndrome." (PMID 41522673, 2026). "In contrast, VPS13C mutations cause early onset Parkinson’s disease, featuring rapid disease progression with atrophy in multiple brain regions, including midbrain." (PMID 40956846, 2025). "In the context of neurodegeneration, it is of interest that a WWE domain is present within the structure of VPS13A, as well as of VPS13C, whose mutations also result in neurodegeneration (Parkinson’s disease)." (PMID 35994651, 2022). "Loss-of-function mutations of VPS13C result in early onset Parkinson's disease (hence the PARK23 designation of this protein), while partial loss-of-function increases Parkinson's disease risk." (PMID 34216812, 2021). "The two other mammalian VPS13 isoforms, VPS13B and VPS13C, have a different subcellular localization, with VPS13C, whose mutations result in Parkinsons disease, acting at contacts between the ER and late-endosomes/lysosomes." (PMID 34046249, 2021). "VPS13C is a multi-exonic gene (86 exons) responsible for early-onset parkinsonism, and it is associated with a severe phenotype characterized by rapid progression, cognitive deterioration, and a widely distributed presence of Lewy bodies." (PMID 29163333, 2017). "VPS13A and VPS13C are bridge-like lipid transport proteins with distinct subcellular localization and function, and their absence is linked with chorea-acanthocytosis and Parkinson's disease, respectively." (PMID 40956846, 2025). "Interestingly, mutations in VPS13C (aka PARK23) cause familial, early-onset Parkinson’s disease, adding to the mounting evidence that mtDNA-mediated innate immune activation is involved in this disease." (PMID 37001140, 2023). "In addition, the loss of VPS13C functioning in early-onset forms of Parkinson disease was recently detected to aggravate PINK1/Parkin-dependent mitophagy." (PMID 31159836, 2019). "Mutations in the vacuolar protein sorting 13 homolog C (VPS13C) gene have been associated with Parkinson disease (PD)." (PMID 41517720, 2026). "A review of the literature indicates that VPS13C-related Parkinsonism appears as a heterogeneous disorder, including PD and dementia with Lewy bodies." (PMID 41517720, 2026). "Here we show that VPS13C, a bridge-like lipid-transport protein and a Parkinson’s disease gene, is a sensor of lysosome stress or damage." (PMID 40211074, 2025). "Vacuolar protein sorting-associated protein 13C (VPS13C), is a protein involved in ER-late endosome/lysosome contact sites and its mutations are a monogenic cause of early onset parkinsonism." (PMID 33769432, 2021). "Loci associated with rare monogenic forms of Parkinson’s disease, or more complex disorders with a prominent component of parkinsonism, also encode proteins involved in vesicle trafficking: VPS35, ATP13A2, PLA2G6, DNAJC6, SYNJ1, and VPS13C." (PMID 33556113, 2021). "The link of VPS13C to Parkinson was discovered shortly after yeast Vps13 was shown to be important for mitochondrial integrity." (PMID 34216812, 2021). "Alterations of vacuolar protein sorting‐associated protein 13 (VPS13) family members including VPS13A, VPS13B, and VPS13C lead to chorea acanthocytosis, Cohen syndrome, and parkinsonism, respectively." (PMID 31876103, 2020). "Additional variants in VPS13C have been identified in further reports on autosomal recessive, early-onset forms of parkinsonism, although not in late-onset PD." (PMID 35328025, 2022).
Parkinson disease (continued). "Notably, a series of Parkinson’s disease (PD)-related genes linked to the endomembrane system, including VPS35, LRRK2, GBA, TMEM175 and VPS13C were also identified indicating that PD proteins may act along the MAPL pathway to regulate immune signalling and cell death." (PMID 41083601, 2025). "Finally, the activation of mitophagy is decreased in parkinsonism with T2DM comorbidity, and increased activation of the protein VPS13C, which delays the progression of mitophagy." (PMID 39429779, 2024). "Suspecting atypical Parkinsonism, a Wilson disease study and genetic tests of Charcot–Marie–Tooth (CMT), atypical Parkinsonisms (PARKs, GAB, DNAJC6, VPS13C, PINK, and LG), and atypical spinal–muscular atrophies (DYNC1H1, BICD, VAPB, GARS, DYNC1H1, mtATP6, and mtATP8) were carried out." (PMID 37510225, 2023).
chorea-acanthocytosis (5 papers, 2016 to 2022). Chorea-acanthocytosis (ChAc) is a form of neuroacanthocytosis and is characterized clinically by a Huntington disease-like phenotype with progressive neurological symptoms including movement disorders, psychiatric manifestations and cognitive disturbances. "Loss of functionmutations in VPS13A and VPS13C cause chorea acanthocytosis and Parkinson'sdisease, respectively." (PMID 36147729, 2022). "Mutations in VPS13A and VPS13B cause the genetic diseases chorea-acanthocytosis (ChAc) and Cohen syndrome, respectively, and a loss of VPS13C function has recently been linked to early-onset Parkinson's disease." (PMID 27329800, 2016). "There are four human homologs (VPS13A–D), and mutations in these genes result in chorea-acanthocytosis (ChAc) (VPS13A), Cohen’s syndrome (VPS13B), early-onset parkinsonism (VPS13C) and childhood-onset movement disorder (VPS13D)." (PMID 33668157, 2021). "Humans express four different VPS13 paralogs, designated A through D. Mutations in VPS13A, VPS13B, VPS13C and VPS13D are associated with the neurodegenerative disorder Chorea-Acanthocytosis (ChAc), Cohen Syndrome, Parkinson’s Disease, and a form of cerebellar ataxia, respectively." (PMID 34201352, 2021).
diffuse Lewy body disease (2 papers, 2021 to 2024). "Recent developments identified VPS13C and D as disease causing mutations in other movement disorders, namely mutations in VPS13C cause autosomal recessive Parkinsons disease/Lewy body disease and VPS13D mutations cause spinocerebeller ataxia with saccadic intrusions (SCAR4)." (PMID 34046249, 2021).
melanoma (2 papers, 2021 to 2024). A malignant, usually aggressive tumor composed of atypical, neoplastic melanocytes. "Intriguingly, patients with primary melanoma or higher tumor stage had significantly worse outcomes, which suggested that AKAP9, VPS13C, ACSL4, and HMOX2 might play a vital role in the overall survival of SKCM through mediating cancer growth and metastasis." (PMID 33663112, 2021). "While investigating the association between expression of hub OS genes and SKCM clinical features, we discovered that patients with metastatic melanoma had significantly increased expression of AKAP9, VPS13C, and ACSL4, while HMOX2 demonstrated higher expression in patients with primary melanoma." (PMID 33663112, 2021).
type 2 diabetes (2 papers, 2016 to 2020). "We investigated the role of VPS13A and VPS13C in GLUT4 translocation to the plasma membrane, as the VPS13C gene locus has been linked to type 2 diabetes risk and glycaemic traits." (PMID 33087848, 2020). "Furthermore, VPS13C RNA encodes for a vascular protein associated with the pathophysiology of type-2 diabetes, which may further support the association of diabetes with dengue severity." (PMID 27286230, 2016).
asthma (1 paper, 2019). "Three known asthma loci replicated in CAAPA, after a Bonferroni correction for 810 association tests: chromosomes 9p24 (RANBP6, IL33), 15q22 (RORA,NARG2,VPS13C), and 17q12–q21." (PMID 30787307, 2019).
dengue (1 paper, 2016). "The model with CCL8, VPS13C RNA, uPAR protein, and with CCL8, VPS13C RNA and platelets were the best biomarker models for stratifying adult dengue patients at early infection, with sensitivity and specificity up to 83% and 84%, respectively." (PMID 27286230, 2016).
Obesity (1 paper, 2024). Accumulation of substantial excess body fat. "The top-altered proteins in our study include VPS13C, ADIPOQ, and IGKV1D-13 which can be used as biomarkers for obesity-related IR and to identify individuals with a future risk for T2D." (PMID 38672154, 2024).
Onset (1 paper, 2025). The age group in which disease manifestations appear. "VPS13C (PARK23) mutations are associated with autosomal-recessive early-onset PD, rapid progression and Lewy body inclusions." (PMID 40362688, 2025).
periodontal disease (1 paper, 2025). "This study reveals the high-expression of VPS13C and MAP1LC3B in periodontal disease and their potential association with mitophagy, suggesting that they may serve as novel targets for regulating chronic inflammation and mitochondrial homeostasis." (PMID 40859550, 2025). "One possibility is that the upregulation of VPS13C and MAP1LC3B in periodontal disease may inhibit mitophagy, thereby exacerbating OS and leading to further tissue destruction." (PMID 40859550, 2025).
periodontitis (1 paper, 2025). An acute or chronic inflammatory process that affects the tissues that surround and support the teeth. "BNIP3L and CTTN were downregulated in periodontitis, correlating negatively with disease prevalence, immune infiltration, and inflammatory pathways, whereas VPS13C and MAP1LC3B were upregulated, showing positive correlations." (PMID 40859550, 2025).
skin cutaneous melanoma (1 paper, 2023). "Recent study revealed that VPS13C (vacuolar protein sorting 13 homolog C) was descended and associated with poor prognosis in skin cutaneous melanoma." (PMID 37700273, 2023).
tumor (4 papers, 2021 to 2025). "Currently, research on the VPS13C gene remains limited; however, our study indicates that higher expression of VPS13C in tumor tissue is associated with improved prognosis, consistent with previous findings." (PMID 39439891, 2024). "Additionally, we observed that tumor-cell-specific isoforms had slightly more exons (paired t-test P-value = 0.01), particularly in genes with more than 20 exons such as NBPF10, VPS13C, and NBPF14." (PMID 37433798, 2023).
movement disorder (3 papers, 2021 to 2025). Neurological conditions resulting in abnormal voluntary or involuntary movement, which may impact the speed, fluency, quality and ease of movement. "This Movement Disorder Society Genetic mutation database Systematic Review focuses on monogenic atypical parkinsonism with mutations in the ATP13A2, DCTN1, DNAJC6, FBXO7, SYNJ1, and VPS13C genes." (PMID 34396589, 2021).
cancer (2 papers, 2021). A tumor composed of atypical neoplastic, often pleomorphic cells that invade other tissues. "Results indicated that the four hub genes were all significantly related to metastasis (P < .05); AKAP9, VPS13C, and ACSL4 were positively associated with metastatic ability, while HMOX2 was negatively associated with cancer metastasis." (PMID 33663112, 2021). "Other genes such as VPS13C, ANKDD1B, and MID2 have been rarely investigated in drug resistance‐related cancer research." (PMID 34026427, 2021). "Therefore, we further investigated connections between AKAP9, VPS13C, ACSL4, and HMOX2 expression and cancer metastasis." (PMID 33663112, 2021).
infection (2 papers, 2016 to 2025). The state of being infected such as from the introduction of a foreign agent such as serum, vaccine, antigenic substance or organism. "Together, our findings highlight the utility of BioID as a tool to study host-pathogen interactions in the context of infection and characterize VPS13C as a novel modulator of the intracellular life cycle of S. Typhimurium." (PMID 40953080, 2025).
neurological diseases (1 paper, 2024). "There are four members of the Vps13 family—Vps13a, Vps13b, Vps13c, and Vps13d—and mutations in each gene cause distinct neurological diseases." (PMID 39063018, 2024).
VPS13C also shares sentences with these, for which no sentence is quoted: Parkinsonism (9 papers); cognitive decline (2); dementia (2); neurodegenerative disease (2); amyotrophic lateral sclerosis (1); Ataxia (1); Cohen syndrome (1); diabetes (1); mastitis (1); metabolic disease (1); metastatic melanoma (1); neurodevelopmental disorder (1); ovarian carcinoma (1); proteinopathies (1); Spasticity (1); Wilson disease (1); –muscular atrophies (1).